SIRPA (signal regulatory protein alpha)
Diseases named in the same sentence as SIRPA in open-access papers (continued):
Sharing a sentence is not in itself a finding about the gene and the disease.
tumor (continued). "Blockade of SIRPα significantly impaired the growth of established tumors by day 11 post-tumor induction compared with isotype control-treated mice." (PMID 38577107, 2024). "Recent studies have highlighted the potential of dual-targeting CD47/SIRPα and PD-1/PD-L1 in inhibiting tumor growth." (PMID 38462636, 2024). "Since SIRPα blockade reverts MDSCs to a less suppressive phenotype and promotes phagocytosis, antigen processing, and presentation of tumor-derived material, we then tested the impact of SIRPα blockade, and its affects, on B16.F10 tumor development in vivo." (PMID 38577107, 2024). "CD47 is usually upregulated on the surface of tumor cells, binding to signal-regulatory protein alpha (SIRPα) on phagocytic cells and inhibiting their phagocytic function, creating a “don’t eat me” signal." (PMID 39148736, 2024). "Its interaction with the signal regulatory protein alpha (SIRPα) on macrophages inhibits apoptosis and supports tumor cell survival." (PMID 38892394, 2024). "CD47, by binding to its receptor signal regulatory protein-alpha (SIRPα) on anti-tumor macrophages, promotes AML cell survival by blocking macrophage phagocytosis." (PMID 38459166, 2024). "CD47 can interact with its receptor signal regulatory protein α (SIRPα) to inhibit the phagocytic activity of DCs and promote tumor immune escape." (PMID 39334927, 2024). "Treatment with PD-1/SIRPα NVs led to a significant 77.2% reduction in tumor weight compared to the PBS group." (PMID 39588148, 2024). "Interaction of CD47 with the signal regulatory protein-alpha (SIRPα) receptor expressed on many myeloid derived cell lineages activates molecular pathways effectively inhibiting an anti-tumor function of innate immunity." (PMID 39742254, 2024). "IgG1 and IgG4 anti-CD47 mAb secreted by oHSV-infected tumor cells blocked the CD47/Sirpα signaling pathway and enhanced the phagocytosis of ovarian tumor cells by macrophages." (PMID 38832992, 2024). "In vitro cellular uptake, tumor-selective binding, and in vivo antitumor efficacy of PD-1/SIRPα NVs were investigated in detail." (PMID 39588148, 2024). "PD-1/SIRPα NVs significantly suppressed tumor growth and elicited a robust antitumor immune response with enhanced immunotherapy efficacy." (PMID 39588148, 2024). "CD47 primarily inhibits the phagocytosis of tumor cells by macrophages by binding to the surface receptor SIRPα and sending a “don’t eat me” signal." (PMID 38370407, 2024). "This suggests that engagement of myeloid cell SIRPα would be predominantly driven via interactions with other stromal components expressing CD47 in addition to those with tumor cells." (PMID 38577107, 2024). "Apart from immune‐independent tumour suppression, we further verified the effect of innate and adaptive anti‐tumour immunity through blocking the SIRPα/CD47 and PD‐1/PD‐L1 pathway in vitro." (PMID 37974395, 2023). "By this, HX009 blocks the binding of CD47 on tumor cells with SIRPα on macrophages and DCs and, therefore, activates macrophage-mediated phagocytosis of the CD47-expressing tumor cells." (PMID 36900399, 2023). "The engineered OAd-SIRPα-Fc and OAd-Siglec10-Fc generated in this study showed outstanding efficacy in tumor suppression in macrophage-dominated tumors." (PMID 38016957, 2023). "Overall, these early trial results indicate that CD47/SIRPα blockade was well tolerated and elicited anti-tumor activity in multiple malignancies." (PMID 37958404, 2023). "Soluble mSIRPαext polypeptides, which possess the extracellular domains of mouse SIRPα, promoted M1 polarization and increased phagocytosis of tumor cells by macrophages." (PMID 37131214, 2023). "6MW3211 was designed with high binding affinity to hPD-L1 and low affinity to hCD47, which allows 6MW3211 to preferentially bind to hPD-L1 expressing tumor cells followed by CD47/SIRPα signaling disrupting." (PMID 36593962, 2023).
tumor (continued). "The interaction of CD47 and SIRPα on macrophages can aid the tumor cells to escape the phagocytic clearance of macrophages, though blocking CD47 can reverse macrophage-mediated tumor inhibition." (PMID 36792608, 2023). "CD47 is a membrane-bound protein that is highly expressed on tumor cells and binds to signal regulatory protein α (SIRPα) on macrophages, delivering a “don't eat me” signal that leads to immune evasion by the tumor." (PMID 37993941, 2023). "CD47 on the tumor surface produces corresponding signals by binding to SIRPα on macrophages, which makes macrophages unable to recognize and phagocytize tumor cells." (PMID 37171006, 2023). "On the other hand, the interaction of cancer cell CD47 with macrophage SIRPα inhibits phagocytosis to promote tumor progression." (PMID 36823443, 2023). "They first showed that the process of neddylation and NEDD8 expression were increased in various cancer types in SIRPα+ tumor-infiltrating macrophages." (PMID 36787255, 2023). "Preclinical tumor models have demonstrated that the abrogation of the CD47/signal regulatory protein alpha (SIRPα) axis is sufficient to trigger DC/NK cell crosstalk." (PMID 37298470, 2023). "One study showed that blocking the CD47‐ signal regulatory proteins α (SIRPα) axis between tumor cells and phagocytes enhanced the phagocytosis of tumor cells by innate immune cells." (PMID 36999977, 2023). "The number of ongoing clinical trials of CD47 and SIRPα antagonists is increasing as strong emerging evidence showed CD47/SIRPα axis blockage promotes tumor control." (PMID 36626230, 2023). "The peritoneal tumor cell–killing model was utilized to assess the role of neddylated SHP2 in the CD47/SIRPα axis in vivo." (PMID 36626230, 2023). "In summary, CD47 expression levels, SIRPα expression levels, tumor-infiltrating immune cells, immune checkpoint expression levels, and TMB are potential biomarkers that can help predict response to CD47-targeted therapy." (PMID 38188674, 2023). "Increased expression of Siglec10, SIRPα, and TIGIT was significantly associated with the infiltration levels of neutrophils and dendritic cells (DCs) in almost all tumor types except THYM." (PMID 38016957, 2023). "Another example is the transfection of the signal regulatory protein alpha (SIRPα) and PD-1 sequences into tumor cells." (PMID 38258033, 2023). "6MW3211 effectively blocked both PD-1/DP-L1 and CD47/SIRPα signaling and promoted macrophage phagocytosis of tumor cells." (PMID 36593962, 2023). "Our results suggested that OAd-SIRPα-Fc and OAd-Siglec10-Fc both showed outstanding efficacy in tumor suppression of macrophage-dominated tumors, while OAd-TIGIT-Fc showed the best antitumor immunity in CD8+ T-cell-dominated tumors." (PMID 38016957, 2023). "The results supported the previous report, in which blockade of SIRPα signalling effectively reduced tumour growth in other animal models and overcame resistance to ICIs." (PMID 36419386, 2023). "While CD47/SIRPα-axis inhibitors in combination with IgA therapy have shown promise, complete tumor eradication remains a challenge, indicating the presence of other checkpoints." (PMID 37444515, 2023). "Conversely, CD47 functions in the tumor microenvironment can depend on the engagement of either SIRPα or TSP1." (PMID 36768931, 2023). "We examined the potential antitumor action of an antibody to human SIRPα (SE12C3) that inhibits the interaction of CD47 on tumor cells with SIRPα on human macrophages and thereby promotes Fcγ receptor–mediated phagocytosis of the former cells by the latter." (PMID 38162643, 2023). "The SIRPα expression of tumor-infiltrating myeloid cells exhibited a large decline in NAC-treated partial response (PR) groups and an increase in groups of NAC-treated patients with progressive disease (PD) or stable disease (SD)." (PMID 36626230, 2023).
tumor (continued). "The addition of anti-PD1 to anti-SIRPα + HRT, on the other hand, greatly suppressed tumor progression in all mice and caused persistent CR in all mice." (PMID 37291116, 2023). "It is a valuable attempt to develop PD‐1/SIRPα fusion HAC NVs as direct immunotherapeutic agents for tumour ICB therapy." (PMID 37974395, 2023). "In the bilateral MC38 tumor model, OAd-SIRPα-Fc treatment achieved greater control of the treated primary tumor and untreated distant tumor than OAd-null therapy." (PMID 38016957, 2023). "We utilized a staining/gating scheme that included Flt3 and SIRPα to establish that the 344SQ tumor infiltrating Ly6C+ monocytes are heterogenous." (PMID 37449205, 2023). "We also demonstrated a sensitive neddylation profile of tumor-infiltrating monocytes/macrophages downstream of SIRPα, which validated that neddylation participated in the reshaping of the tumor immune microenvironment." (PMID 36626230, 2023). "It has been proved that QPCTL inhibitors can block the recognition effect of CD47 on SIRPα and restore phagocytic function of macrophages, and enhance the anti-tumor effect in vivo." (PMID 37484024, 2023). "We then determined the interaction between CD47 on tumor cells and SIRPα on macrophages in vitro and in vivo." (PMID 36959204, 2023). "Notch activation repressed SIRPα expression through the Hes family co-repressors and then enhanced tumor cell lysis partly by promoting polarization into the M1 phenotype." (PMID 37131214, 2023). "CD47 expressed on tumor cells binds to signal regulatory protein alpha on macrophages, initiating inhibition of phagocytosis." (PMID 36598153, 2023). "These agents are designed to block the interaction between CD47 and SIRPα to relieve suppression of cancer cell phagocytosis by APCs in order to stimulate tumor immunity." (PMID 37958404, 2023). "In cancer therapy, recombinant soluble SIRPα can bind to CD47 on tumor cells and disrupt the CD47-SIRPα interaction on macrophages, inducing phagocytosis of tumor cells." (PMID 37111479, 2023). "In phagocytic synapse (right side), the binding of signaling regulatory protein alpha (SIRPα) on macrophage to CD47 on AML (or other tumor cell) results in inhibition of phagocytosis." (PMID 37020553, 2023). "The tumor micro-environment features a marked expression of SIRPα, an inhibitory receptor present on myeloid cells, as well as its widely distributed counter-receptor CD47." (PMID 38283146, 2023). "Interaction of CD47 on tumor cells with SIRPα on TAMs thus constitutes an innate immune checkpoint that interferes with the detection and phagocytosis of the former cells by the latter." (PMID 38162643, 2023). "In vitro phagocytosis of tumor cells expressing miR-30a-3p or miR-30e-3p by macrophages was significantly enhanced after CD47/SIRPα blockade." (PMID 37446353, 2023). "CD47 is an important anti-phagocytosis signal, which can prevent the phagocytosis of tumor cells by macrophages via binding to ligand signal regulatory protein α (SIRPα) on macrophages." (PMID 37334368, 2023). "Although macrophages have the potential to kill tumors, tumor cells can promote tumor cell expansion and growth by binding to SIRPa on the surface of macrophages in tumor-infiltrating areas through high expression of CD47." (PMID 36627482, 2023). "They further showed that combining SIRPα–Fc antibodies with VEGF inhibition potentiated anti-tumor efficacy by increasing macrophage-mediated phagocytic uptake of cancer cells and inhibiting the formation of new blood vessels in tumors." (PMID 37958404, 2023). "The high affinity of 6MW3211 to hPD-L1 and low affinity to hCD47 was supposed to navigate 6MW3211 to hPD-L1 expressing tumor cells followed by disrupting CD47/SIRPα interaction." (PMID 36593962, 2023). "CD47 is an immunosuppressive molecule that binds SIRPα on antigen-presenting cells to regulate an innate immune checkpoint that blocks phagocytosis and subsequent activation of adaptive tumor immunity." (PMID 37958404, 2023).
tumor (continued). "Immunoblot analysis showed that tumor cells infected with OAd-SIRPα-Fc, OAd-Siglec10-Fc or OAd-TIGIT-Fc efficiently secreted the corresponding fusion protein as a dimer into the supernatant in vitro." (PMID 38016957, 2023). "To explore the role of MPs and NPs in tumour growth of SIRPα‐KO mice, we depleted these cells by i.p. injection of clodronate liposomes and anti‐Ly6G (αLy6G) antibody, respectively, 1 day before tumour inoculation of LLC cells and every 5 days afterwards." (PMID 36419386, 2023). "To further develop ICI targeting CD47, we need to better understand the functions of its interactions with TSP1 and SIRPα in the tumor microenvironment." (PMID 36768931, 2023). "In summary, CD47 can play different functional roles in tumour or immune cells by binding to SIRPα on the cell surface or to the secreted TSP1 protein." (PMID 38037074, 2023). "This inequivalent binding affinity design makes 6MW3211 preferentially bound to PD-L1 on tumor cells followed by disrupting the interaction of CD47/SIRPα." (PMID 36593962, 2023). "Inhibition of isoQC blocks the interaction between CD47 and SIRPα, leading to constrained tumor growth." (PMID 38125492, 2023). "CD47 is frequently overexpressed on tumor cells and plays a key role in tumor escape by binding to SIRPα and sending macrophages a ‘don't eat me’ signal." (PMID 36911370, 2023). "Weissman’s team found that almost all cancer cells had high levels of CD47, and the large amount of CD47 expression interacts with macrophages’ SIRPα, which the tumor clearance ability of macrophages." (PMID 37484024, 2023). "In SCLC, the blockade of ‘do not eat me’ signals conveyed by CD47 expression on tumor cells and its interaction with signal regulatory protein alpha (SIRPα) on macrophages increased phagocytic activity of macrophages and inhibited tumor growth." (PMID 36809334, 2023). "To characterize the precise effects of OAds, we evaluated antitumor activity in three tumor models established with immunocompetent mice treated with an intratumoral injection of OAd-null, OAd-SIRPα-Fc, OAd-Siglec10-Fc, or OAd-TIGIT-Fc." (PMID 38016957, 2023). "Most tumors contain the surface receptor CD47 that interacts with the signal-regulating protein α (SIRPα) on phagocytes and reduces the ability of macrophages to phagocytize tumor cells." (PMID 37373342, 2023). "CD47/SIRPα blockade elicits anti-tumor activity by facilitating macrophage phagocytosis, which is amplified by CD40 signaling." (PMID 37345054, 2023). "Employing CD47-overexpressed T-EVs instead of anti-CD47 antibodies to block CD47/SIRPα signal has the advantage that T-EVs can carry therapeutics to kill tumor cells around macrophages, thus “killing two birds with one stone”." (PMID 37283792, 2023). "In macrophages, integrin activation was shown to be inhibited by positioning of SIRPa in the phagocytic synapse after ligation of tumor-expressed CD47." (PMID 38138970, 2023). "Consistent with our observations, we noted a clear increase in the prevalence of SIRPA+MSR1+-expressing macrophage subpopulations in tumour tissues (77.3% of all macrophages) compared with normal tissues (24.6% of all macrophages)." (PMID 36442992, 2023). "So, phagocytosis can be enhanced by the blockade of the CD47-Signal Regulatory Protein α (SIRPα) axis using different molecules to prevent the interaction between CD47 expressed on tumor cells and SIRPα expressed on macrophages." (PMID 37175226, 2023). "Results derived from tumor studies in the NOD strain of mice are further complicated by the fact that human CD47 binds to NOD-Sirpα with 10× greater affinity than to human SIRPα." (PMID 37958404, 2023). "Innate ICIs achieve anti-tumor purposes by targeting checkpoints such as SIRPα, TIGIT, PVRIG, LILRB2, NKG2A, LAG-3, TIM-3, VISTA and CD32B." (PMID 37510993, 2023). "SIRPα-Fc was able to disrupt CD47/SIRPα interactions by blocking CD47 in tumor cells, redirecting macrophages to the tumor site and killing the tumor cells." (PMID 37993941, 2023).
tumor (continued). "For cancer immunotherapy, Rao's group prepared tumour targeting cell vesicles (CVs) by fusion of individual CV components expressing PD‐1 or SIRPα, respectively." (PMID 37974395, 2023). "The results showed that OAd-SIRPα-Fc injection enhanced the proportion of CD8+ T cells in MC38 tumor tissues more significantly than Ad or OAd-null injection." (PMID 38016957, 2023). "Both SIRPα-Fc fusion proteins effectively abolished the anti-tumor efficacy of HIP CAR T cells as assessed by BLI." (PMID 37037829, 2023). "While we show that the CD47/SIRPα axis is a key regulator in tumor growth, tumors frequently exploit multiple mechanisms to avoid immune surveillance." (PMID 37444515, 2023). "CD47, a receptor of signal regulatory protein α (SIRPα), is one of the “don’t eat me” signals expressed on healthy cells and frequently over-expressed on tumor cells." (PMID 37345054, 2023). "Drugs targeting CD47 can enhance macrophage phagocytosis in the special environment of tumor tissue and promote macrophage recruitment to tumor by directly blocking the binding of SIRPα to CD47." (PMID 37484024, 2023). "Considering the relevance of the CD47/SIRPα axis in tumor progression, including under (chemo)-therapeutic pressure, several novel studies have demonstrated the potential of CD47-based combination therapies in different types of cancer." (PMID 37153563, 2023). "The blockade of CD47 with anti-CD47 or anti-SIRPα antibodies resulted in increased rates of experimental tumor eradication after RT." (PMID 37232754, 2023). "The “don’t eat me” signal transmitted by CD47 on tumor cells contributes to the inhibition of their phagocytosis by interacting with signal regulatory protein-alpha (SIRPα) displayed by macrophages." (PMID 37476156, 2023). "As part of immune evasion, myeloid cells express signal regulatory protein α (SIRPα) to inhibit phagocytosis by phagocytes in the tumor microenvironment (TME)." (PMID 37291116, 2023). "At the same time, the combination of ferritin expressing SIRPα resulted in complete tumor eradication in 8 of the 9 mice." (PMID 36999977, 2023). "The principle basis for testing biologicals targeting human CD47 using xenograft tumor models revolves around the fact that the polymorphic SIRPα in NOD mice interacts with human CD47, supporting the growth of xenografts." (PMID 37012357, 2023). "On the surface of tumor cells, CD47 binds to SIRPα, inhibiting macrophage-mediated phagocytosis, which is an important means of tumor immune escape." (PMID 37049910, 2023). "MC38 tumor-bearing C57BL/6 mice were given either anti-SIRPα antibody, HRT (12 Gy), or both to study this concept." (PMID 37291116, 2023). "For exploring if HRT triggers SIRPα upregulation in TME, we removed the tumor tissue under flow cytometric testing of SIRPα expression on myeloid cells at different time points after performing HRT on MC38 tumors with 12 Gy." (PMID 37291116, 2023). "Anti-SIRPα antibodies that target CD47-SIRPα axis have been reported to show promise in promoting anti-tumor immunity." (PMID 38239430, 2023). "Overall, SIRPα/CD47 blockade results in a therapeutic strategy for cancer treatment that involves macrophages as key players in tumor immune escape." (PMID 36829496, 2023). "Pep-20 was able to block the interaction between CD47 and SIRPα, thereby enhancing the macrophage-mediated phagocytosis of tumor cells." (PMID 37108657, 2023). "Our findings confirm that CD47/SIRPα is an important myeloid checkpoint that regulates neutrophil killing of tumor cells." (PMID 37444515, 2023). "Tumour‐derived mediators induce M2 cell polarisation, IL‐6 expression in macrophages and neutrophils through SIRPα/SHP‐1/p38 MAPK/STAT3 signalling." (PMID 36419386, 2023). "The present findings are consistent with a model in which the addition of anti-SIRPα to local HRT can transform the TME into a tumor-killing niche heavily populated by activated CD8+ T cells, but with limited MDSC and TAM." (PMID 37291116, 2023).